CD4 (CD4 molecule)
Diseases named in the same sentence as CD4 in open-access papers (continued):
Sharing a sentence is not in itself a finding about the gene and the disease.
Arthritis (340 papers, 2004 to 2026). Inflammation of a joint. "Our previous work identified increased CTLA‐4 expression in joint‐localized dendritic cells and CD4+ T cells following nanoparticle treatment, which was associated with reduced arthritis severity and protection against bone and cartilage damage." (PMID 41244342, 2025). "Specifically, among CX3CR1+ age-associated T cells, an increase in CD4+ T cells reflects the activity of arthritis and the degree of inflammatory markers." (PMID 39910629, 2025). "SKG CD4+ T cells are required to cause arthritis, and even naive CD4+ (CD4+naive) T cells transferred into immunodeficient hosts trigger disease." (PMID 39589811, 2024). "It has been shown that FPR2 ligation inhibits the expansion of effector pathogenic CD4+ T cells in two arthritis models, whereby FPR2 signaling enhances IL17 production in CD4+ T cells, while leaving IFNγ unchanged." (PMID 39148732, 2024). "We found that γδ T cells and NK cells were linked with mucosal ulcer, CD8+ T cells were associated with vasculitis, CD4+ T cells were associated with arthritis, NKT cells were related to AIHA, and Tregs were associated with LN." (PMID 35130317, 2022). "The γδ T cells high group and NK cells high group were significantly related to higher frequency of mucosal ulcer, and the CD4+ T cells high group was significantly associated with higher rate of arthritis." (PMID 35130317, 2022). "The CD4+ T cells high group was significantly associated with arthritis, and the NKT cells high group was substantially linked with autoimmune hemolytic anemia." (PMID 35130317, 2022). "For example, a lower proportion of CD8+ effector cells is associated with arthritis, while a higher proportion of CD4 TH2 cells and CD4 TH17 cells at baseline is related to pneumonitis and thyroiditis, respectively." (PMID 35774996, 2022). "Collectively, these data obtained in vivo suggest that the loss of SIGIRR expression in CD4 T cells results in enhanced susceptibility to antigen-induced arthritis." (PMID 36401167, 2022). "An AIA mouse model (antigen-induced arthritis) and CD4 T cells transfer experiments were performed to investigate the effect of SIGIRR deficiency on the development of arthritis in vivo." (PMID 36401167, 2022). "Our study demonstrated that γδ T cells were not important for the progression of arthritis, however their contribution to the generation of pathogenic CD4+CCR6+ T cells during arthritis cannot be excluded." (PMID 31778214, 2020). "Arthritis in Ptpn2-haploinsufficient SKG mice is associated with accumulation of G protein–coupled receptor 15–positive CD4+ T cells." (PMID 33055428, 2020). "Here, we used genome-wide molecular profiling to comprehensively investigate the relationship between RA-associated genetic variants, DNAm, and gene expression in primary CD4+ T and B cells of drug-naive patients with early arthritis." (PMID 31945409, 2020). "The role of CD4+ T-cell-derived GM-CSF has been implicated in autoimmune tissue inflammation in mouse models of neuroinflammation, arthritis, and myocarditis." (PMID 33193343, 2020). "CD4+ T cells have a major role in the development of serum-transfer arthritis, as mutation of the T-cell receptor and formation of autoreactive T cells are key features of the model." (PMID 31551776, 2019). "Myeloid cells of lymphatic vessels and spleen producing IL-6 andIL-1β are responsible for an increase in the amount of Bregs associatedwith arthritis, while CD4+ splenic T cells producing IL-21 activateBregs in experimental arthritis models." (PMID 30397522, 2018). "SKG arthritis is dependent on CD4 T cells, because arthritis can be induced in T cell deficient mice by the adoptive transfer of CD4 T cells." (PMID 28753982, 2017). "After cell sorting, the arthritis-associated pathogenic role of CD4+CD28−OX40+ T cells was investigated." (PMID 28320444, 2017).
Arthritis (continued). "And, anti-inflammatory effects of A77 1726 shown in arthritis mice are associated with inhibited oxidative damage and selective HO-1 induction in CD4+ T cells." (PMID 28193225, 2017). "We also demonstrated that CD4+ induced IELs with TCRs capable of causing arthritis and those from WT mice had a phenotype and suppressive capability similar to those associated with CD4+2D2-IEL-THIGH cells." (PMID 27198196, 2016). "We show the inhibitory capacity of CD4+ induced IELs with another TCR associated with arthritis and with the polyclonal TCR of WT mice." (PMID 27198196, 2016). "Previous reports have shown that arthritis is associated with the presence of Th1 CD4+ T effector cells secreting high levels of IFN-γ while there is an absence of Th2 effectors in the arthritic synovium in murine CIA models and RA." (PMID 26379475, 2015). "TCR repertoires are likely to be important in autoimmunity because it has been shown in JIA that T cell clonotype expansions mirror the HLA class I (CD8 expanded) or class II (CD4 expanded) association of arthritis." (PMID 26561546, 2015). "The results demonstrate that PGRN-deficient CD4+CD25- T cells have an impaired ability to generate iTreg in arthritis conditions." (PMID 25393765, 2014). "Our data suggests that protection from arthritis induced with anti-CD4 is associated with an overall decrease of infiltrating T cells in synovial tissue and, within those T cells in the synovium, with an increase in the frequency of synovial Foxp3+ Treg cells." (PMID 20479941, 2010). "In mice with collage-induced arthritis, depletion of CD4+CD25high regulatory T cells causes rapid progression, and the transfer of isolated and ex vivo-proliferated CD4+CD25high regulatory T cells can reverse early joint damage." (PMID 19046457, 2008). "Our previous work also identified increased CTLA‐4 expression in joint‐localized dendritic cells and CD4+ T cells following treatment with calcitriol‐loaded nanoparticles, which was associated with reduced arthritis severity and protection against bone and cartilage damage." (PMID 41244342, 2025). "Antiretroviral treatment and Sag-reactive T cell depletion curtailed SKG arthritis, suggesting that endogenous retroviruses disrupted peripheral tolerance and promoted the activation and differentiation of autoreactive CD4+ T cells into pathogenic effector cells." (PMID 39589811, 2024). "Additionally, we assessed the impact of rTs-Pmy on CD4+ T cell differentiation towards the Th1 and Th17 phenotypes, which are associated with inflammatory responses in arthritis, using in vitro assays." (PMID 38928413, 2024). "Tryptophan, the rarest essential amino acid, may be associated with the development of arthritis through its effects on the activation of CD4+ T cells and the production of autoantibodies." (PMID 39221139, 2024). "Similarly, IL-18R alpha-deficient mice exhibited an attenuated form of arthritis with reduced synovial CD4 T cell and macrophage infiltration as well as lower serum levels of IL-6, IL-18, TNF-α and IFN-γ as compared to WT mice." (PMID 37415987, 2023). "In this model SKG CD4 T cells are sufficient and necessary to cause arthritis." (PMID 34923645, 2022). "Moreover, the arthritis scores of CIA mice were indicated to be more associated with the population of CD19+ICOSL+ B cells when compared with CD4+ICOS+ T cells (r = 0.4657, P = 0.0025 vs r = 0.3720, P = 0.0181)." (PMID 36405702, 2022). "Thus, human MSC administration to mice with established collagen-induced arthritis was accompanied by a reduced level of pathogenic CD4+T cells in the spleen and peripheral blood." (PMID 34090507, 2021). "Evaluation of immune cells in lymphoid organs showed that injection of SR-A protein caused elevation of IL-17A in the serum associated with increased frequency of IL-17A-producing CD4+ T cells, implicating a linkage of the sSR-A activity with a pathogenic Th17 response in arthritis." (PMID 32312978, 2020).
Arthritis (continued). "Intracellular cytokine staining of splenocytes showed that, in addition to Th17 cells, lack of SR-A also dramatically reduced the frequency of Th1 cells, i.e., TNF-α-producing CD4+ T cells, underscoring an important role of SR-A in arthritis-associated inflammation." (PMID 32312978, 2020). "Reduced circulating and lymph nodes CD4+IL-10+ T cells have been reported in subjects at risk for RA, with a subsequent increase in peripheral CD4+IL-17A+ T cells in close relationship with the onset of the arthritis." (PMID 31295951, 2019). "Against this backdrop, we set out to reassess the biologic landscape of candidate susceptibility genes in RA by mapping cis‐ and trans‐eQTLs at 101 established RA risk loci in circulating CD4+ and B lymphocyte subsets sampled from a cohort of untreated patients with early arthritis." (PMID 29193869, 2018). "Our study not only corroborates the previous findings of an AhR cell autonomous role in CD4 T cells for arthritis development, but identify that the major environmental risk for RA development, cigarette smoking, induces disease aggravation through an AhR-dependent increase in Th17 cell response." (PMID 29884199, 2018). "While γδ17 and Th17 cells may have complementary pathogenic roles in the development of IL1rn−/− arthritis, our data suggest that IL-17-producing cells located in lamina propria and induced by IL1rn−/− intestinal microbiota are TCRβ-expressing CD4+ Th17 cells." (PMID 28645307, 2017). "Interestingly, a recent report also demonstrated that TOFA attenuates arthritis manifestations and reduces the pathogenic IFNγ+CD4+ splenic T cells in adjuvant arthritis rats." (PMID 28830352, 2017). "Using this model, we have confirmed that activation of a large number of DR1-restricted autoimmune CD4+ T cells enhances the severity of the arthritis, and this phenomenon is associated with both increased numbers of autoantibodies and enhanced levels of inflammatory cytokines." (PMID 24405551, 2014). "This is in keeping with the overall protective role of IFN-γ in CIA and a recent study reporting selective deficiency of Ahr, a transcription factor for IL-22, in CD4 T cells being associated with reduced arthritis and increased Th1 response but an unaltered Th17 response." (PMID 24676270, 2014). "Thus, arthritis produced in these mice by the F759 mutation in gp130 required not only homeostatic CD4+ T-cell expansion but upregulation of IL-7 gene expression in nonhemopoietic cells as well." (PMID 20339519, 2009). "Conceiveably, our observations with regard to PADI4 and IKZF3 could be interpreted as evidence that putatively common causal SNPs augment gene expression in CD4+ T cells uniquely under the particular biologic and/or environmental circumstances of early arthritis." (PMID 29193869, 2018). "Furthermore, among the four T-cell subsets transferred to CIA mice, CD4+CD28−OX40+ T cells displayed the most significant pathogenic role in arthritis development compared with CD4+CD28−OX40− (P = 0.011), CD4+CD28+OX40− (P < 0.001), and CD4+CD28+OX40+ (P < 0.001) T cells." (PMID 28320444, 2017). "Additionally, the presence of OX40 may neutralize costimulation of CD28, which may impair arthritis pathogenic roles of CD4+CD28+OX40+ T cells." (PMID 28320444, 2017). "Moreover, this highly inflammatory milieu is associated with a persistent imbalance of the CD4+ effector T/regulatory T cell ratio in SF weighted toward effector T cells, such that the higher the ratio the longer the post-antibiotic duration of arthritis." (PMID 24286535, 2013). "Depletion of Sag-reactive subsets in transfer studies of CD4+ T cells into SCID recipients also delayed arthritis onset." (PMID 39817448, 2025). "C3H/HeJ mice are an ideal model for the study of Lyme arthritis because they also develop an IFN-γ-producing Th1 response and expansion of CD4+ T cells subsets that are heavily involved in the development of severe arthritis." (PMID 40793757, 2025).
Arthritis (continued). "We found that arthritis activity in the D2T RA group correlated with the proportion of CX3CR1+CD4+ T cells." (PMID 39910629, 2025). "The proportion of CX3CR1+CD4+ T cells was positively correlated with arthritis activity and inflammatory marker levels." (PMID 39910629, 2025). "The loss of LAT1 can inhibit Th17 cell differentiation, reduce the number of proinflammatory cells such as IFN-γ+ CD4+ T cells and TNF-α+ CD4+ T cells, maintain the quantity and suppressive capacity of nTregs, and significantly alleviate arthritis." (PMID 39917294, 2025). "Engineered Anti‐CD4 mAbs(anti‐arthritis) bind to CD4 (different epitopes) to suppress arthritis in rat models." (PMID 40988381, 2025). "CX3CR1+CD4+ T cells were found to be positively correlated with arthritis activity and age in patients with D2T RA." (PMID 39910629, 2025). "In the murine CIA model, they found increased intestinal permeability prior to arthritis onset, and by using mice expressing photoconvertible proteins, they showed that CD4+T cells migrated from small intestines to arthritic joints." (PMID 40639878, 2025). "This has been demonstrated in animal experiments where arthritis can still be induced despite the depletion of CD4+ T cells." (PMID 40051059, 2025). "Mice that received SKG CD4+ T cells depleted of most Sag-reactive Vβs exhibited a significant delay in arthritis onset and a trend toward less severe disease." (PMID 39589811, 2024). "Rag2R229Q hypomorph and ZAP70skg mouse models exemplify human partial T cell immunodeficiencies wherein CD4+ T cells were shown to be necessary for intestinal inflammation and arthritis, respectively." (PMID 37962568, 2024). "The high Mg2800 diet reduced arthritis severity and joint damage and reduced synovial inflammation and the expression of cytokines while increasing the numbers of CD4+Foxp3+ Treg cells and IL10-producing Tr1 cells." (PMID 39683640, 2024). "It is also worth noting that IL-7-induced proliferation of CD4 T cells induces arthritis in a murine model of RA." (PMID 39554252, 2024). "Accordingly, our data demonstrate abundant clonal expansion within circulating cytotoxic CD4+ T cells, with an increase in circulating clone abundance coincident with the onset of arthritis flare." (PMID 38316770, 2024). "Transfer of CD4+CD25+ cells into immunized mice during induction of antigen-induced arthritis resulted in reduced arthritis severity." (PMID 38322264, 2024). "The result indicated that the CD4+T cell proliferation ability of BCII-induced arthritis mice was high." (PMID 38268530, 2024). "Studies have proved that blockade of CD127 can decrease the number of CD4+ and CD8+ T cells and the associated cytokines, which in turn, halt the development of inflammatory diseases, including allergic asthma and arthritis." (PMID 37905596, 2024). "Exploratory mass cytometry analyses reveal three circulating cellular subsets heralding the onset of arthritis flare – CD45RO+PD1hi CD4+ and CD8+ T cells, and CD27+CD86+CD21- B cells – further characterised by single-cell sequencing." (PMID 38316770, 2024). "Sulf2+/− bone marrow chimeric mice showed significantly increased joint swelling and histological damage in the resolution phase of the macrophage- - and CD4+ T cell-dependent antigen-induced arthritis model." (PMID 39141086, 2024). "This study explores the gene expression and TCR repertoire in arthritogenic SKGNur GFPhi CD4+naive T cells before arthritis onset." (PMID 39589811, 2024). "Remarkably, a high frequency of PD-1hiHLA-DR+CD4+ T cells persisted in their joints for up to 2.5 years after the onset of arthritis, correlating with ongoing synovitis despite prior antibiotic treatment and concurrent antiinflammatory medication." (PMID 38963700, 2024). "The inhibitor tofacitinib has been shown to decrease the production of IL-17 and IFN-γ and the proliferation of CD4+ T cells in cells derived from patients with arthritis." (PMID 37373437, 2023).
Arthritis (continued). "In another study using a collagen-induced arthritis model, transfer of IL-32β-producing CD4+ T cells aggravated arthritis, which was attenuated by TNF-α blockade." (PMID 36875066, 2023). "When Exo-FBS or Exo-RA was administered to the collagen-induced arthritis model, serum interleukin (IL)-4 and the proportion of Th2 (CD4+CD25+GATA3+) and M2 (CD11c − CD206+ of CD45+CD64+) cells were significantly increased compared to the control group." (PMID 37794417, 2023). "CD4+ T cell-specific D2r deletion exacerbated both the polarization towards Th1 and Th17 cells and the symptoms of arthritis." (PMID 37237413, 2023). "In a model of severe combined immunodeficiency (SCID), mice develop arthritis after an adoptive transfer of primed autoreactive CD4+ Th1-cells followed by a challenge with the auto-reactive target." (PMID 36901730, 2023). "Sustained miR-34a expression in CD4+ T cells from RA patients or arthritis mouse models influences cellular Foxp3 expression, altering Treg cell polarization/generation and aggravating RA progression." (PMID 35625530, 2022). "Depletion of CD4 + T lymphocytes in mBSA/IL-1-induced arthritis led to dose-dependent T cell proliferation in draining lymph nodes in response to mBSA." (PMID 35210510, 2022). "In our proof-of-concept study to demonstrate the potential of controlling Th17 cells by targeting TGF-β signalling, we included as positive control anti-IL17 treatment, since the arthritis model we used is known to be dependent on CD4 + T cells and IL-1720,53." (PMID 35210510, 2022). "The frequency of IFNγ+ CD4+ T cells and Th1 cells was significantly decreased after treatment for arthritis-irAE, whereas the frequency of IL-17+ CD4+ T cells, t-Th17 cells, and Th17 cells was unchanged after treatment." (PMID 35413951, 2022). "Specifically, CD4+ T cells mediate chronic CHIKV-associated joint swelling and in mouse models, the presence of CD4+ T cells are obligatory for the development of arthritis." (PMID 36275717, 2022). "Methylated BSA/IL-1-induced arthritic mice treated with neutralizing IL-4 antibody showed a 30% reduction in arthritis, suggesting IL-4 regulates CD4 T cell-dependent arthritis." (PMID 35163028, 2022). "Radionuclide imaging of CD4 in arthritis adds to imaging of fibroblasts activating protein and F4/80 receptor positive macrophages." (PMID 36114433, 2022). "Germ-free SKG mice transplanted with fecal bacteria from RA patients and induced with zymosan would develop severe arthritis, with an increase in the number of CD4 + T cells and IL-17-producing T helper (Th17) cells in the intestine." (PMID 36699603, 2022). "Treg depletion exacerbated AIA, whereas adoptive transfer of CD4+CD25+ Treg cells attenuated arthritis." (PMID 35874732, 2022). "For example, MPO knockout mice exhibited an enhanced response of CD4+ T cells in lymph nodes, aggravating arthritis." (PMID 35912260, 2022). "In this sense, VPAC2 has also been shown to be the predominant receptor in PBMC in early arthritis in different experimental conditions, such as activated memory Th cells, Th17-polarized cells, and proinflammatory CD4+CD28− T cells." (PMID 35955723, 2022). "We demonstrated that ZIP8 was specifically upregulated in CD4+ T cells that infiltrated the inflamed joint and that ZIP8 deficiency in CD4+ T cells abrogated collagen-induced arthritis." (PMID 33795795, 2021). "have shown that a combined inhibition of glutamine metabolism and mTOR significantly suppressed CD4+ T cell activation-mediated arthritis in mice better than each monotherapy, implying the essential role of cellular metabolism in immune cell mTOR signaling." (PMID 33897705, 2021). "In this model, at the time of first clinical arthritis symptoms, specific effector CD4 T cells were undetectable in the synovial fluid and rare in the blood, but persisted in the lymph nodes." (PMID 34380700, 2021).